SERPINE2 (serpin family E member 2)
Diseases named in the same sentence as SERPINE2 in open-access papers (continued):
Sharing a sentence is not in itself a finding about the gene and the disease.
emphysema (5 papers, 2010 to 2019). "Another study conducted in Japanese population showed association of rs975278 of SERPINE2 with emphysema under recessive model." (PMID 24587150, 2014). "Our results support the previously found association between SERPINE2 polymorphisms and pulmonary emphysema." (PMID 22145704, 2011). "In the current study, the stratified analysis revealed a two-fold risk for developing panlobular emphysema for homozygous variant genotypes of SERPINE2 rs729631 SNP." (PMID 22145704, 2011). "We aimed to further examine the role of SERPINE2 polymorphisms in the development of pulmonary emphysema and different emphysema subtypes." (PMID 22145704, 2011). "In conclusion, our findings support the suggested association between SERPINE2 genotypes and development of pulmonary emphysema." (PMID 22145704, 2011). "The SERPINE2 rs729631 SNP, which was associated with panlobular emphysema in the whole study population, showed statistical significance also in both sub-cohorts." (PMID 22145704, 2011). "The present study revealed that a SERPINE2 SNP (rs975278) was associated with pathologically diagnosed emphysema in consecutive autopsies of Japanese smokers." (PMID 21067581, 2010). "We believe that SERPINE2 is a good candidate gene that is associated with emphysema, as diagnosed using CT." (PMID 21067581, 2010). "The present study revealed that a polymorphism in SERPINE2 (rs975278) was associated with emphysema in consecutive autopsies of Japanese subjects." (PMID 21067581, 2010). "Among the 12 examined SNPs, only rs975278 in the SERPINE2 gene was positively associated with emphysema." (PMID 21067581, 2010). "In this study, the association of SERPINE2 polymorphism with emphysema was more prominent among the smokers." (PMID 21067581, 2010). "Our finding that SERPINE2 polymorphism is associated with emphysema appears to be consistent with the findings of these previous studies that reported positive associations, as assessed using physiological parameters of lung function." (PMID 21067581, 2010). "In agreement with this, our recent findings suggested that SERPINE2 gene polymorphisms may be involved particularly in the development of panlobular emphysema." (PMID 23734748, 2013). "In addition to the current study, two previous studies have reported association between SERPINE2 genotypes and emphysema." (PMID 22145704, 2011). "In addition, another research group recently associated SERPINE2 polymorphism with autopsy diagnosed emphysema among Japanese smokers." (PMID 22145704, 2011). "This suggests that SERPINE2 variants contribute to the risk of developing emphysema in smokers." (PMID 21067581, 2010). "SERPINE2 may be a risk factor for the development of emphysema and its association with emphysema may be stronger in smokers." (PMID 21067581, 2010). "Thus, our finding that a SERPINE2 variant is associated with emphysema may indicate that this variant influences the severity of lung destruction rather than the presence or absence of chronic pulmonary obstruction." (PMID 21067581, 2010). "SERPINE2 belongs to the same serpin-superfamily of proteins as AAT, a gene deficiency of which is known to cause emphysema, especially the panlobular type emphysema." (PMID 22145704, 2011). "This suggests that the disease phenotype behind the observed association between SERPINE2 and COPD might indeed be structural emphysema." (PMID 22145704, 2011). "Two study groups have recently reported an association between SERPINE2 and emphysema, but no previous study has assessed the role of SERPINE2 polymorphisms in structurally different emphysema subtypes." (PMID 22145704, 2011). "However, the mechanism by which SERPINE2 contributes to the development of emphysema remains to be elucidated." (PMID 21067581, 2010). "Thus, accumulating evidence shows that SERPINE2 is a susceptible gene of COPD and a modifier of COPD related phenotypes, but its relation with emphysema remains unknown." (PMID 21067581, 2010).
osteosarcoma (5 papers, 2021 to 2024). A usually aggressive malignant bone-forming mesenchymal neoplasm, predominantly affecting adolescents and young adults. "Our investigation into osteosarcoma (OS) prognosis concerning apoptosis-related genes found that high SERPINE2 and CPT1B expression correlates with poor survival." (PMID 38383657, 2024). "SERPINE2 increased osteosarcoma cell growth and treatment resistance." (PMID 37124542, 2023). "SERPINE2 may drive self-proliferation and drug resistance in osteosarcoma, and has poor prognosis for patients with bladder and ovarian cancer with high COL1A2 expressions." (PMID 36428591, 2022). "In our study, the prognostic model identified certain genes, notably SERPINE2 and CPT1B, as having a strong correlation with the prognosis of osteosarcoma (OS)." (PMID 38383657, 2024). "Dysregulation of SERPINE2 and CPT1B, along with lymphocyte imbalances, emerges as a pivotal molecular pathway in the etiology of osteosarcoma (OS)." (PMID 38383657, 2024).
bladder cancer (4 papers, 2021 to 2024). "Elevated SERPINE2 expression in bladder cancer is associated with a reduced overall survival rate, suggesting its utility as a predictive biomarker for patient prognosis in this malignancy." (PMID 38383657, 2024). "SERPINE2 has also been identified as a significant player in bladder cancer, where its expression levels are tightly linked with patient outcomes." (PMID 38383657, 2024). "Previous studies demonstrated that high SERPINE2 expression was related to worse OS, adverse pathologic features and may serve as a prognostic biomarker for bladder cancer, which was consistent with our findings." (PMID 38274096, 2023). "TCGA database analysis found that high SERPINE2 expression was a predictor of poor prognosis for both OS and DFS in patients with bladder carcinomas (Kaplan–Meier plots and log-rank test, p < 0.01 for both OS and DFS)." (PMID 34679626, 2021).
colon carcinoma (4 papers, 2010 to 2025). "Our analysis identified Serpine2 as a key factor associated with the enhancement of fibroblast–epithelial cell interactions, contributing to colon cancer progression and metastasis." (PMID 40642075, 2025). "Through subgroup analyses, we confirmed a strong association between Serpine2 expression and colon cancer metastasis." (PMID 40642075, 2025). "Given that Serpine2 has been implicated in the metastasis of other cancer types, we also gathered clinical data regarding colon cancer metastasis during patient recruitment." (PMID 40642075, 2025). "In alignment with stroma-associated colon cancer markers, such as MMPs, Serpine2 is predominantly secreted by stromal cells and plays a functional role in this context." (PMID 40642075, 2025). "Concurrently, we have identified Serpine2 as a potential molecular marker associated with Fn-promoted colon cancer progression, with its expression predominantly localized to fibroblasts." (PMID 40642075, 2025). "Furthermore, Serpine2 has been identified as a potential molecular marker associated with Fn-mediated colon cancer progression and metastasis." (PMID 40642075, 2025). "Our findings provide valuable insights into the role of Serpine2 in Fn-mediated colon cancer progression." (PMID 40642075, 2025). "Secondly, single-cell sequencing data from animal models suggested that Fn infection promotes colon cancer progression through upregulation of Serpine2, which we further verified by RNA-seq of Fn co-cultured with HT29 and CT26 cells, respectively." (PMID 40642075, 2025). "While previous studies have reported elevated levels of Serpine2 in colon adenocarcinoma, the specific molecular mechanisms by which Serpine2 promotes colon cancer progression at the scRNA-seq level remain unexplored." (PMID 40642075, 2025). "Due to its complex regulatory mechanisms, elucidating SERPINE2 and its potential regulatory mechanisms will help understand the pathogenesis of colon cancer." (PMID 40463876, 2025). "While these regulatory molecules have been predicted, further investigation is required to elucidate their role in modulating Serpine2 and promoting colon cancer metastasis." (PMID 40642075, 2025). "In future research, the upstream mechanisms of Serpine2 in colon cancer metastasis should be further explored through experimental screening and validation." (PMID 40642075, 2025). "Subsequently, we continued to induce THP-1 with recombinant SERPINE2 protein and then co-cultured it with colon cancer cells." (PMID 40463876, 2025). "We collected clinical samples from patients with colon cancer and reaffirmed the potential of Serpine2 as a molecular marker for Fn-promoted colon cancer progression." (PMID 40642075, 2025). "Compared to other family members, SERPINE2 showed a high expression level and was closely related to clinical malignant progression of colon cancer patients." (PMID 40463876, 2025). "Cell co-culture experiments further demonstrated that SERPINE2 secreted by colon cancer cells can induce polarization of M2 macrophages." (PMID 40463876, 2025). "In this study, we want to investigate the potential mechanism of SERPINE2 in tumor microenvironment of colon cancer." (PMID 40463876, 2025). "Immune infiltration analysis indicated a significant positive correlation between SERPINE2 and M2 macrophage infiltration, and tissue chip confirmed the correlation between SERPINE2 expression in colon cancer tissues and macrophage infiltration." (PMID 40463876, 2025). "Not only at the mRNA and protein levels, but also the extracellular secretion of SERPINE2 shows a significantly upregulated expression in colon cancer cells." (PMID 40463876, 2025). "These investigations offer insights into how Fn may facilitate colon cancer progression through the enhancement of Serpine2 expression." (PMID 40642075, 2025).
colon carcinoma (continued). "This loop is crucial for the proliferation and metastasis of colon cancer, suggesting that the signaling cascade initiated by SERPINE2 may be a potential therapeutic target." (PMID 40463876, 2025). "Furthermore, we identified a significant correlation between Serpine2 expression levels and the progression of colon cancer, as determined by the pathological stage of the patients." (PMID 40642075, 2025). "Our study demonstrates that tumor-secreted SERPINE2 mediates a positive feedback loop between tumor cells and M2 macrophages to accelerate cancer progression, suggesting SERPINE2 may be as a promising therapeutic target for colon cancer treatment." (PMID 40463876, 2025). "These THP-1-derived macrophages (PMA-THP-1) were further stimulated with SERPINE2 recombinant protein to obtain activated macrophages (SERPINE2).The results showed that the mRNA level of SERPINE2 was upregulated in colon cancer cell lines compared to normal colon cell NCM460." (PMID 40463876, 2025). "However, we found that Serpine2 mRNA expression level was significantly correlated with the pathological stage of colon cancer, and Serpine2 gene expression level with deeper stage." (PMID 40642075, 2025). "Mechanically, we have described that the secretion of SERPINE2 by colon cancer cells may induce M2 polarization of macrophages." (PMID 40463876, 2025). "Specifically, Fn may be appears to stimulate fibroblasts to release exosomes enriched with Serpine2, which subsequently act on colon cancer cells to enhance their metastatic potential." (PMID 40642075, 2025). "This indicates that serpinE2 controls anchorage-independent growth of human colon carcinoma cells." (PMID 20942929, 2010). "Finally, in vitro transwell migration assays were performed to verify the importance of serpinE2 in colon carcinoma cell migration." (PMID 20942929, 2010). "We then verified whether the reduction in serpinE2 expression alters the ability of colon cancer cells to form colonies in soft agarose." (PMID 20942929, 2010). "Indeed, the very oncogenic receptor tyrosine kinase MET was also shown to promote serpinE2 gene expression in a xenograft colon tumor model." (PMID 20942929, 2010). "This suggests that Serpine2 may possess pro-metastatic potential in colon cancer." (PMID 40642075, 2025). "Furthermore, there is a notable gap in understanding how Serpine2 expression changes within the tumor microenvironment following Fn infection, which may drive colon cancer progression." (PMID 40642075, 2025). "Furthermore, the expression level of CD68 was significantly increased in the cancer tissues with high expression of SERPINE2, suggesting that the high expression of SERPINE2 in colon cancer may promote macrophage infiltration." (PMID 40463876, 2025). "However, preliminary results (data not shown) indicate that the phosphorylated levels of Akt and ERK1/2 were not affected following serpinE2 depletion in colon carcinoma cells." (PMID 20942929, 2010).
lung adenocarcinoma (4 papers, 2020 to 2023). A carcinoma that arises from the lung and is characterized by the presence of malignant glandular epithelial cells. "In this study, we examined the expression of SERPINE2 in 74 consecutive lung adenocarcinoma cases by immunohistochemistry using an anti-SERPINE2 antibody." (PMID 33317533, 2020). "The expression levels of SERPINE2 in 74 consecutively resected lung adenocarcinomas were analyzed by using immunostaining." (PMID 33317533, 2020). "SERPINE2 expression was significantly correlated with lymphatic invasion (P = 0.0188), suggesting that lung adenocarcinomas that express SERPINE2 show aggressive features." (PMID 33317533, 2020). "A consecutive series of 74 specimens of completely resected adenocarcinoma of the lung were examined for SERPINE2 expression." (PMID 33317533, 2020). "The current study demonstrated the role of SERPINE2 as an independent prognostic factor of lung adenocarcinomas and its molecular mechanism for the first time." (PMID 33317533, 2020). "In lung adenocarcinomas in particular, high expression of SERPINE2 has been previously reported, but the relationship to prognosis or disease progression has never been reported." (PMID 33317533, 2020). "SERPINE2 was more expressed in several cancers, including BRCA, CHOL, COAD, HNSC, KIRC, KIRP, lung adenocarcinoma (LUAD), Lung squamous cell carcinoma (LUSC), READ, ESCA, LIHC, THCA." (PMID 38274096, 2023). "However, SERPINE2 expression and its role in lung adenocarcinomas are still unknown." (PMID 33317533, 2020). "In addition, we silenced SERPINE2 in two kinds of non-small cell lung cancer (NSCLC) cell lines using siRNA and performed a cell number assay and evaluation of apoptosis to clarify the cell-autonomous function of SERPINE2 in lung adenocarcinoma cell lines." (PMID 33317533, 2020).
Obesity (4 papers, 2017 to 2024). Accumulation of substantial excess body fat. "Fas cell surface death receptor (Fas), versican (Vcan), T-box transcription factor 21 (Tbx21), angiotensin I converting enzyme (Ace), and serpin family E member 2 (Serpine2), metabolic markers associated with obesity, were increased in the obese group." (PMID 38728395, 2024). "Gfra1, Or56b2j, Serpine2, and Tecrl were the only genes previously annotated with obesity-related traits." (PMID 38483771, 2024). "Additionally, genes FSTL3, QSOX1 and SERPINE2 could serve as novel obesity-related biomarkers, as they have been shown to be uniquely enriched in the placenta, and we detected them as down-regulated among the placentas from obese women." (PMID 28125591, 2017).
adenoma (3 papers, 2010 to 2025). A neoplasm arising from the epithelium. "Additionally, Serpine2 expression is markedly upregulated in adenomas with Apc mutations." (PMID 40642075, 2025). "5- Finally, Q-PCR analyses demonstrated that mRNA levels of serpinE2 were markedly increased in human adenomas in comparison to healthy adjacent tissues and in colorectal tumors, regardless of tumor stage and grade." (PMID 20942929, 2010). "MRNA levels of serpinE2 were markedly increased in human adenomas in comparison to healthy adjacent tissues." (PMID 20942929, 2010). "Accordingly, we found a significantly higher level of serpinE2 mRNA when comparing affected tissues from advanced adenomas and carcinomas to adjacent healthy tissues." (PMID 20942929, 2010). "The strong expression of serpinE2 in human adenomas suggests that this secreted protein might be a potential blood biomarker for early diagnosis of tumors in the colon and the rectum." (PMID 20942929, 2010). "Furthermore, serpinE2 is overexpressed in human adenomas and colorectal tumors compared to the adjacent healthy tissues." (PMID 20942929, 2010).
COVID-19 (3 papers, 2021 to 2024). A disease caused by infection with severe acute respiratory syndrome coronavirus 2. "Furthermore, we observed that the major transcript of multiple genes switched to a different transcript (isoform switching) between COVID-19 patients and controls, such as IL2, IL34, SERPINE2, NCBP1, HRAS, PRPF6, NCBP2, and LUC7L2." (PMID 35421082, 2022).
glioblastoma (3 papers, 2015 to 2023). The most malignant astrocytic tumor (WHO grade IV). "The results shown that SERPINE1 was the highest expression in glioblastoma multiforme (GBM), SERPINE2 was the highest expression in kidney renal papillary cell carcinoma (KIRP), and SERPINE3 was the highest expression in cholangiocarcinoma (CHOL)." (PMID 38274096, 2023). "Serpine2 expression seems to vary across tumor stages and tissue types, and its exact role in glioblastoma is not yet known, but it seems to be abundant in glioblastoma, whereas its expression is very low in meningioma." (PMID 36717781, 2023).
lung fibrosis (3 papers, 2015 to 2024). "SERPINE2 encodes a serine protease inhibitor with activity toward thrombin, trypsin, and urokinase, although its role in lung fibrosis has not yet been defined." (PMID 38612561, 2024). "These are clear evidences showing the involvement of serpinE2 in the lung fibrosis, but whether it mediates cardiac fibrosis is unclear." (PMID 36439874, 2022).
metastatic cancer (3 papers, 2006 to 2026). A carcinoma which has spread from the original site of growth to another anatomic site. "This review synthesizes multi-omics insights into SERPINE2-driven microenvironmental reprogramming and discusses emerging therapeutic strategies integrating molecular targeting and immunotherapy in metastatic cancers." (PMID 42099617, 2026). "Examples of these unique genes include Serpine2, which is overexpressed in metastatic cancer; Ctnnb1, Fliih, Pdlim4/Ril, all of which affect migratory behavior of cells; and Gas6, which is a ligand for the Axl oncogene." (PMID 17147824, 2006).
metastatic tumors (3 papers, 2015 to 2018). "Serpine2 was also found to be more secreted by K14+ cells, and its expression and secretion have been correlated with metastatic disease." (PMID 29924804, 2018).
Myocardial fibrosis (3 papers, 2017 to 2025). "SERPINE2 was previously reported to promote the myocardial fibrosis by activating the ERK1/2 and β-catenin signaling pathways." (PMID 39754051, 2025). "Previous studies reported that SERPINE2 might play an important role in fibrotic diseases, such as myocardial fibrosis and pulmonary fibrosis." (PMID 39754051, 2025). "Recently, in a model of myocardial fibrosis, both AT-II and TGF-β were reported to mediate fibrosis by increasing the levels of serpinE2/protease nexin-1, which is responsible for collagen deposition." (PMID 28751931, 2017).
papillary thyroid cancer (3 papers, 2017 to 2024). "Knockdown of SERPINE2 in human papillary thyroid cancer cells decreased the antiapoptotic protein Bcl-2 and increased the proapoptotic protein Bax and caspase-3, thereby promoting cell apoptosis." (PMID 36505099, 2022). "SERPINE2 has been found to have an integral role in papillary thyroid cancer, where its expression may affect tumor progression and patient prognosis." (PMID 38383657, 2024). "The aim of this study was to assess serum SERPINE2 and SLPI concentrations in a group of 36 patients with papillary thyroid cancer (PTC) and a group of 19 subjects with multinodular nontoxic goiter (MNG)." (PMID 28255192, 2017).